IL10 (interleukin 10)
Diseases named in the same sentence as IL10 in open-access papers (continued):
Sharing a sentence is not in itself a finding about the gene and the disease.
infection (continued). "Likewise, IL-10 would also participate in infection control given its inverse correlation with infected hepatocytes, although the underlying mechanism is not clear from the global analysis of our results." (PMID 34414132, 2021). "Other studies have shown that IL-10 is produced at 6 h after infection with UPEC in vivo." (PMID 34835359, 2021). "Our results suggest the occurrence of different regulatory mechanisms depending on the infection stage because the Y-infected mice displayed higher percentages of IL-10-producing cells at 10 dpi and increased percentages of Foxp3HiCD25+ and LAP+ cells at 30 dpi." (PMID 34712620, 2021). "IL-10 plays a central role in infection and has anti-inflammatory properties." (PMID 34564576, 2021). "Therefore, C. jejuni-challenged secondary abiotic IL-10-/- mice were treated perorally with either cumin-EO or placebo starting on day 2 post-infection." (PMID 34209990, 2021). "Consistent with this study, our study also found that serum IL-10 only increased in acute patients, indicating that IL-10 may only be involved in the early stage of infection." (PMID 34592958, 2021). "Interleukin (IL)-17, IFN-γ, TNF-α, and IL-10 may be critical to the host survival and infection control." (PMID 34869064, 2021). "This might be due to anti-inflammatory nature of IL-10 that prevents NK and T cell activities to affect the strong inflammatory action after first infection." (PMID 33766078, 2021). "IL-10 levels in the rN-BmRON2 group increased after infection, reaching a peak on the 21st day." (PMID 33717108, 2021). "At later time points after infection, H3K18la-mediated anti-inflammatory (such as IL-10 and Arg1) overexpression may be related to late death." (PMID 35069560, 2021). "Notably, the proinflammatory factor IL-6 and anti-inflammatory factor IL-10 were both increased during infection." (PMID 34593766, 2021). "Immunologically, anti-il-10 antibodies inhibited the anti-colitic effect of H. diminuta-infection." (PMID 34517928, 2021). "Coxiella burnetii induces expression of STAT3 and IL-10 during murine infection." (PMID 33789347, 2021). "Transcription of IFN-γ and IL-10 in the caeca at 5 days post infection was assessed by RT-qPCR." (PMID 33693044, 2021). "Following peroral infection with 109 viable bacterial cells, C. jejuni could stably establish in the intestinal tract of microbiota-depleted IL-10−/− mice with high median numbers of 109 CFU per gram large intestinal content." (PMID 34209438, 2021). "In addition to Tregs, other immune cell populations can contribute to IL-10 production constitutively or in a dynamic fashion during infections." (PMID 33746948, 2021). "The overproduction of the liver cytokine IL-10 in IFN-γ KO mice 2 days post-infection compared to the production in wild-type mice (35 ng/mL vs. below detection limit, respectively) could explain the underlying response." (PMID 34204632, 2021). "In addition, we found that systemic IL-6 and IL-10 levels in patients with an SFTSV infection more strongly correlated with outcomes (for severe disease with an ultimate outcome of recovery or death) than did viral load and neutralizing antibodies." (PMID 34484214, 2021). "Although it can eliminate or promote infection with differing intensity and duration at different infectious phases, the presence of IL-10 decreases Chlamydia eradication via anti-inflammatory action, and is helpful for controlling and minimizing Chlamydia-induced diseases and complications." (PMID 34093528, 2021). "The durability of IL-10-producing CD4+ T cells post-infection demonstrated how this cytokine may contribute to optimizing the control of parasites and prevent immunity-mediated pathology during recurrent malaria infections." (PMID 34414129, 2021). "The IL-10 is one of the anti-inflammatory cytokines, which could prevent damage and infection in pigs." (PMID 34573566, 2021).
infection (continued). "First, they showed that STAT3 activation was associated with IL-10 production by NK cells during Lm infection by detecting phosphorylated STAT3 (p-STAT3) in the lysates of NK cells purified from Lm-infected B6 mice at both 24 h and 72 h post-infection." (PMID 35053151, 2021). "To determine if IL-10 expression altered the MLNs’ inflammatory context, we aerogenically infected B6 and pMT-10 mice with M. tuberculosis–mCherry and characterized M. tuberculosis–infected myeloid populations at day 14 after infection." (PMID 34554927, 2021). "In conclusion, the different timing of infection may indeed explain the single peak versus two peaks in the IL-10 temporal profiles." (PMID 33788832, 2021). "The activities of CD8+ are modulated by IL-10 depending on the stage of infection." (PMID 34603287, 2021). "Furthermore, IL-10 reduces inflammation during infections, preventing the onset of deleterious lesions." (PMID 34070451, 2021). "In addition, Il6, Il10, and Tnfα mRNA levels were also increased at 4 h post-infection, then reduced at 24 h post-systemic S. aureus infection." (PMID 34040603, 2021). "Furthermore, studies in IL-10-reporter mice showed that IL-10+ ASCs are already found in naïve mice, while LPS administration or infection with Salmonella rapidly expands ASCs that transiently upregulate IL-10 production." (PMID 33995344, 2021). "In addition, after challenge infection, we observed a reduction of IL-1β expression, and modulation of TNFα, TGFβ and IL10 expression." (PMID 33499363, 2021). "These in vitro data suggest that IL-10 expression in neutrophils is directly induced by S. pneumoniae PAMPs present in the bacterial surface but not by soluble host or bacterial factors secreted to the airways during infection." (PMID 33995357, 2021). "We found that many cytokines messenger RNAs (mRNAs), including Il1b, Il5, Il6, Il10, Il12a/Il12p70, Ifng, Ccl4, Ccl5, Tnfa, Gcsf, Cxcl1, Il1a, and Il3, were significantly induced upon B.1.351 infection in the lungs of hACE2 transgenic, BALB/c, and C57BL/6 mice." (PMID 34907154, 2021). "To determine whether parasite load/and or antigen availability plays a role in determining the level of iMo activation, we re-infected B6.Il10-/- mice at d56 p.i., a time at which they had cleared their primary infection." (PMID 34557190, 2021). "Considering this possibility, a major aim of this study was to elucidate whether the production of IL-10 by neutrophils is triggered directly by S. pneumoniae or whether is mediated by host factors released in response to the infection." (PMID 33995357, 2021). "Therefore, IL-10 is considered a dominant controlling signal for suppressing neutrophil migration into the infection site." (PMID 33795743, 2021). "Therefore, the reduced expression of CXCR3 seen on Ag-specific CD4+ T cells from pMT-10 mice overexpressing IL-10 in early stages of infection likely plays a crucial role in the delayed migration of these cells into the lung parenchyma." (PMID 34554927, 2021). "Together our data support a model wherein, during M. tuberculosis infection, IL-10 acts intrinsically on T cells, impairing their parenchymal migratory capacity and ability to engage with infected phagocytic cells, thereby impeding control of infection." (PMID 34554927, 2021). "However, an increase in IL-10 expression and a decrease in the number of neutrophils were observed 48 hours after infection." (PMID 34925324, 2021). "We then performed the crystal violet staining 7 days post infection to further detect whether treatment with IL-10 could influence the cell viability and in vitro oncolytic capacity by the Ad-hTERT." (PMID 33717103, 2021). "Therefore, secondary abiotic IL-10-/- mice were orally infected with C. jejuni strain 81-176 and garlic-EO treatment via the drinking water was initiated on day 2 post-infection." (PMID 34070612, 2021).
infection (continued). "These modules are enriched for negative regulation of cytokine production and activated T cell proliferation, and IL-10 production, which represent anti-inflammatory strategies aimed at host protection via limiting excessive immune activation during an infection." (PMID 33837217, 2021). "Additionally, mice with mixed-biofilm catheters (SE + CT and SE > CT) demonstrated the most severe infection when compared with monomicrobial biofilm catheters as indicated by these parameters, except for serum IL-10." (PMID 34746032, 2021). "In addition, we assess the post-traumatic infections by biomarkers of post-traumatic inflammation IL-6, IL-10, CRP, and WBC." (PMID 34568354, 2021). "However, at 10 weeks post-infection, significantly higher IL-10 and IFN-γ production was observed in animals treated with Hsp65-producing L. lactis-compared to the empty group." (PMID 34248935, 2021). "Similarly, in our study we found that anti-inflammatory IL-10 produced by peritoneal leukocytes is the main component in the cytokine milieu surrounding these parasites in the late stage of infection." (PMID 33461599, 2021). "The role of the IL-10 cytokine can vary significantly depending on the site of infection." (PMID 34204632, 2021). "IL-10 responses have been described post-infection of cattle." (PMID 33782422, 2021). "Results indicated that protein lysates of splenocytes from the B6.il10−/− recipients of NK cells from wt but not from IL-10-deficient mice contained IL-10 protein at 96 h post-infection." (PMID 35053151, 2021). "IL-10-/- mice had improved viral clearance and survival after infection relative to WT mice." (PMID 34777390, 2021). "Interestingly, we found that the expression of immunosuppressive factors, such as IL‐10, was significantly down‐regulated upon H37Rv infection." (PMID 34632719, 2021). "B.1.351 infection in mice resulted in efficient virus replication with high titers in lungs and tracheas, severe pathological lung lesions, and inflammatory responses with elevated IL-6 and IL-10 expression." (PMID 34907154, 2021). "In the brainstem, it was observed an increase of pro-inflammatory cytokines, such as IL-1β, IL-12(p70), IL-13, and TNF-α; chemokines, such as CCL2, CCL3, CCL4, CCL11, CXCL10, and CXCL1; growth factors, such as G-CSF, GM-CSF, M-CSF, and anti-inflammatory IL-10 at ten days post-infection." (PMID 33917837, 2021). "These alterations were accompanied with the elevated transcriptional level of 10 innate immune genes with infection time, where il-1b, il-6, il-8, and il-10 exhibited a higher expression at 33°C than at 18°C and was attenuated by exogenous myo-inositol in both groups." (PMID 34566956, 2021). "Thus, the immunosuppressive effect of IL-10 in synergy with IL-6, probably supports viral persistence or secondary infection, resulting in the more severe clinical outcome in influenza A(H1N1)pdm09 virus." (PMID 34946862, 2021). "We then assessed the transcriptional profiles of pro-inflammatory cytokines Interleukin-6 (IL-6) and interleukin-15 (IL-15) and anti-inflammatory interleukin-10 (IL-10) under normal or iron-depleted conditions and determined how these were affected by infection." (PMID 34571900, 2021). "To determine whether IL-10 production during ZIKVBR infection contributed to the blunted CD8 T cell response, we infected WT and Il10−/− mice with ZIKVBR and assessed the impact of IL-10 deficiency on the antigen-experienced CD8 T cell response 7 dpi." (PMID 34193875, 2021). "Similarly, the production of antibodies and cytokines such as IL-10 by the B cell lineage can dramatically alter mast cell function and provide a long-term mechanism for heightened responses to secondary infection." (PMID 34566974, 2021). "Given that IL-10 plays an important role in the attenuation of inflammation, this result suggests that IL-10 signaling in adipocytes might contribute to promote lipid storage and maintain energy demand in the case of acute responses such as infection." (PMID 34576181, 2021).
infection (continued). "Our analysis supports a model in which cytokine production by inflammatory macrophages at sites of infection may result in increased concentrations of systemic IL-6 and IL-10, promoting the expansion of myeloid cells expressing the MS1 gene program." (PMID 34103408, 2021). "A significant increased value was shown in C-TIM, suggesting that IL-17 exerts a favorable modulator role on cytokines responsible for the resistance to infection, in contrast to the anti-inflammatory prevalence due to IL-10 values recorded in the dC-TIM group." (PMID 35059328, 2021). "However, the expression of the anti-inflammatory cytokines IL-2, IL-10, IL-13, IL-17 was increased in the Rictor knockout mice, both at baseline and after infection, the results are in line with previous reports." (PMID 34650053, 2021). "Importantly, these CD4+ T cells maintained their vasculature phenotype and were unable to control infection, even after adoptive transfer into low IL-10 settings." (PMID 34554927, 2021). "Our findings indicate that B cell-derived IL-10 may contribute to maintaining a compromised immune status in the host, thereby allowing the slowing growth of the parasites or their second infection." (PMID 34552973, 2021). "However, in the S. Gallinarum group, downregulation of expression of both the cytokines (IL-4 and IL-10) mRNA was evident at 6 h post-infection in comparison to mock-treated cells." (PMID 34446765, 2021). "An expansion of IL-10+ Bregs has been detected in patients with parasite infections." (PMID 33995344, 2021). "IL-10 has an active role in enhancing the infection sensitivity of immune cells." (PMID 34925532, 2021). "The excess production of IL-10 in our infection-naïve model might then be partially explained as a response to the overexpression of its proinflammatory inhibition targets." (PMID 34475490, 2021). "However, similarly to spleen cell cultures, decreased IFN-γ levels and increased TNF-α and IL-10 levels were observed in kidney cell cultures after 19 days of infection." (PMID 34575795, 2021). "However, depletion of uNK cells rescues LPS-induced preterm birth in IL10-null mice, indicating they contribute to infection/inflammation-induced preterm parturition." (PMID 33522483, 2021). "Due to strong positive correlation between local TNF-α and IL-10 concentration and lung pathology, we hypothesize that these cytokines are involved in the induction of lung lesions during investigates infection." (PMID 33407470, 2021). "The decrease expression of IL-10 of rHuN4-F5-ORF1b infection may be due to the role of Nsp9 and Nsp10 which were the core components of the membrane-associated viral replication and transcription complex and influence virus replication." (PMID 35062244, 2021). "Annexin B30 was detected in Cs-ESP and triggers strong interleukin 10 (IL-10) production in splenocytes, which might affect the immune response host during infection." (PMID 33530324, 2021). "Type-I T cells produced type-I cytokines, such as IL-2, TNF-α, and IFN-γ, to enhance cellular response to remove infected cells, whereas Type-II T cells produced type II cytokines, such as IL-4, IL-5, and IL-10, to increase antibodies to attack exogenous antigen to prevent host-cell infection." (PMID 34200327, 2021). "Interestingly, NK cells exposure to IL-10 in combination with IL-15, mediated IL-10 release and as a result mediated infection persistence." (PMID 33815404, 2021). "In a similar set of experiments, AMs obtained from control, D. pigrum 040417- and D. pigrum 030918-treated infant mice were challenged in vitro with S. pneumoniae serotype 3, and the levels of IFN-β, IFN-γ, IL-10, and IL-27 in culture supernatants were assessed 24 h post-infection." (PMID 34207076, 2021).
infection (continued). "In all patients, nominal significant differences between the most frequent haplotype and any of the other non-rare haplotypes (haplotype frequency ≥5%) identified were revealed for endpoint rejection and IFN-γ (p = 0.023) as well as infections and IL10 (p = 0.017)." (PMID 33861738, 2021). "Another study showed that MZ B-derived IL-10 inhibits NO synthesis on neighboring metallophilic macrophages, increasing the intracellular survival of Listeria, and facilitating the trans-infection of DCs, which leads to increased bacterial burden, but also to efficient CD8+ T cell priming." (PMID 33995344, 2021). "In addition, a newly identified population of human cord blood CD5hi cells was found to secrete IL-10 upon infection by the respiratory syncytial virus (RSV), leading to inhibition of anti-viral responses and a worse clinical outcome." (PMID 33995344, 2021). "Serum IL-10 and Lm burdens in the spleen and liver were significantly reduced, whereas more inflammatory myeloid cells accumulated in the spleens of NKIl10R− mice compared with B6 mice at 72 h post-infection." (PMID 35053151, 2021). "We began by testing the impact of IL-10 overexpression during the early stages of infection." (PMID 34554927, 2021). "Regarding useful potential biomarkers in the treatment of SAH patients as well as for prediction of outcome and post-SAH infections, serum IL-10 might be an additional useful parameter." (PMID 34064048, 2021). "Moreover, IL-10 production in monocytes was increased after infection with the intracellular bacteria, L. monocytogenes, Legionella pneumophila, Mycobacterium avium, or Salmonella typhimurium." (PMID 35087852, 2021). "However, some clear trends have emerged, including the upregulation of ifnγ in response to myxozoan infection, often followed by a massive spike in il10 expression." (PMID 34603313, 2021). "However, the effects of IL-10 on HIV-1 pathogenesis seem to differ according to the stage of infection, thus indicating a complex relationship between IL-10 levels and HIV-1 disease progression." (PMID 34987508, 2021). "Interestingly, a discrepancy can be discerned in post-infection IL-10 dynamics: some studies reported a single peak, whereas others reported two peaks." (PMID 33788832, 2021). "At late stages of infection, these IL-10-producing NK cells may induce an increased parasite burden in 21-day-infected recipient mice, which suggests that they inhibit host protective immunity against L. donovani." (PMID 35053151, 2021). "Importantly, neonatal B cells are regulated by type I interferon (IFN-α/β) on their capacity to moderate inflammation upon infection via IL-10." (PMID 33535570, 2021). "When we assessed the cytokines production in the spleen and liver of the animals, we observed higher levels of IL-6 in neutropenic animals 1- and 2-days post infection together with an increased level of IL-10 in the liver of these animals 2-days post infection." (PMID 34642440, 2021). "In contrast to our results, the authors observed a significant increase in the production of IFN-γ in the lymph nodes, as well as in the number of specific CD4 T lymphocytes producing IFN-γ at the site of infection, along with a decrease in the production of IL-10." (PMID 34247195, 2021). "During infection, young mice also have higher levels of macrophage infiltration, immune pathology, delayed viral clearance, and delayed antibody production, suggesting the lower levels of IL-10 delay the switch from innate to adaptive responses." (PMID 33680987, 2021). "Using C. jejuni-infected IL-10−/− mice as an in vivo ‘leaky gut’ model, high-dosage cholecalciferol added to their drinking water reversed the infection-induced increase in colonic permeability to fluorescein, confirming the results of our in vitro experiments." (PMID 34445577, 2021).